FER1L4 (fer-1 like family member 4 (pseudogene))
Diseases named in the same sentence as FER1L4 in open-access papers (continued):
Sharing a sentence is not in itself a finding about the gene and the disease.
tumor (22 papers, 2015 to 2025). "High expression of FER1L4 was linked to tumor grade, stage, metastasis and tumor aggressiveness and patient survival." (PMID 35928868, 2022). "Of note, the distinct features of FER1L4 and CDH4 in cancer may be caused by the heterogeneity of tumor, suggesting the great potential for FER1L4 and CDH4 as diagnostic biomarkers of PTC." (PMID 34289835, 2021). "FER1L4 functions as a ceRNA by sequestering miR-106a-5p in gastric cancer, thereby impacting tumor suppression." (PMID 37627777, 2023). "One such lncRNA, FER1L4 (long noncoding RNA Fer-1 protein 4), has been shown to play crucial regulatory roles in tumor progression." (PMID 37627777, 2023). "This research group additionally confirmed the tumor suppression behavior of miR-106a in HCC by indicating the role of Fer-1-like family member 4 (FER1L4) in tumor progression via reducing miR-106a and miR-372 levels in the liver." (PMID 37627777, 2023). "In oral squamous cell carcinoma, FER1L4 facilitated tumor progression through regulation of miR-133a-5p/Prx1 axis." (PMID 35928868, 2022). "Lastly, overexpression of FER1L4 levels increased tumor growth in vivo, which was inhibited by impeding NF-κB." (PMID 33868788, 2021). "FER1L4 was highly expressed and miR-106-5p and miR-372-5p were poorly expressed in tumor cells and tissues." (PMID 33868788, 2021). "Previous studies have shown that FER1L4 plays anti-tumor roles in suppressing cancer cell proliferation and metastasis as well as inducing cancer cell apoptosis." (PMID 34158566, 2021). "Bioinformatic analysis, RT-qPCR, RNA pull down assay and dual luciferase assay showed that FER1L4 upregulated F-box/WD repeat-containing protein 7 (FBXW7) tumor suppressor via sponging miR-92a-3p." (PMID 32140077, 2020). "Our study shows that the lncRNA Fer1L4 is significantly overexpressed in ccRCC tissue, and that high Fer1L4 expression levels are indicative for tumor aggressiveness and cancer recurrence." (PMID 31965534, 2020). "Despite the general assumption of its function as a tumor suppressor, both underexpression and overexpression of Fer1L4 have been described." (PMID 31965534, 2020). "Based on this impact on tumor progression and its influence as an independent prognostic factor, Fer1L4 appears to exert properties as an oncogene in ccRCC." (PMID 31965534, 2020). "Earlier studies investigated the expression and possible influence of Fer1L4 on tumorigenesis in various other tumor entities." (PMID 31965534, 2020). "This heterogenic influence of Fer1L4 on oncogenesis shows that its function on tumor biology is yet incompletely understood." (PMID 31965534, 2020). "The most well-characterized role of FER1L4 is its tumor suppressor function as a negative regulator of AKT signaling in cancers." (PMID 32140077, 2020). "It was demonstrated that Fer1L4 influences cell proliferation as a tumor suppressor by acting as a competing endogenous RNA." (PMID 31965534, 2020). "Besides, overexpressing FER1L4 led to an increased tumor growth in nude mice, which was reversed by the NF-κB inhibitor pyrollidine dithiocarbamate (PDTC)." (PMID 33868788, 2021). "Hence, FER1L4 promoted tumor growth by increasing the level of drug resistance, while that of which was inhibited by NF-κB inhibitor PDTC." (PMID 33868788, 2021). "Overexpressing FER1L4 increased tumor growth in vivo but was reduced by PDTC." (PMID 33868788, 2021). "Taken together, Fer1L4 expression is different in various tumor entities and may exercise as well as oncogenic and tumor suppressive effects." (PMID 31965534, 2020). "Recently, the lncRNA Fer-1 like family member 4 (Fer1L4) was shown to play a role in tumor biology." (PMID 31965534, 2020). "Fer1L4 expression significantly correlates with aspects of tumor aggressiveness." (PMID 31965534, 2020). "Later, several studies suggested that FER1L4 could function as an oncogene or a tumor suppressor in different cancer types." (PMID 32140077, 2020).
tumor (continued). "In vivo experiments confirmed that the down‐regulation of FER1L4 inhibited tumour growth in vivo." (PMID 30887657, 2019). "As a result, we assumed that the tumor suppression effect of miR-106a inhibitors might indirectly through the overexpression of FER1L4." (PMID 26306906, 2015). "Specifically, genes such as TRIM71, DBH, HP, FER1L4, and GCH1 exhibited dynamic and progressive expression changes along tumor grades, with significant increases in Grade 4 tumors compared to Grade 1 (Wilcoxon test, adj." (PMID 41347690, 2025). "In this study, lncRNA Fer-1 like family member 4 (FER1L4) was identified as an oncogene that promoted the proliferation, migration, and invasion of PTC cells via functioning as ceRNA for tumor suppressor miR-612." (PMID 34289835, 2021). "It showed that depletion of FER1L4 delayed the tumor growth of TPC-1 cells, and the tumor size and final tumor weight in implanted tumors significantly decreased in the FER1L4 knockdown group." (PMID 34289835, 2021). "Tumor suppressive lncRNAs (GAS5, MEG3, FER1L4 and LINC00672) and oncogenic lncRNAs (CCAT2, BANCR, NEAT1, MALAT1, H19 and Linc-RoR) have been identified as key regulators of the established tumor suppressor or oncogenic pathways in EC." (PMID 30781521, 2019). "Expression analysis of the excised tumor tissues revealed that compared to the sh-NC group, the sh-RBM15 group exhibited decreased expression of RBM15, KDM5B, and KCNQ1OT1, and increased expression of FER1L4 (p < 0.01)." (PMID 39039611, 2024). "Except for GVINP1 and NCF1C, the expression of the other 5 prognosis-related DE pseudogenes (DDX12P, FER1L4, NSUN5P2, PLEKHA8P1 and RP9P) were higher in tumor tissues than in cutting edge normal tissues, which was totally consistent with the results of TCGA samples." (PMID 36272991, 2022). "Tumor suppressive lncRNAs (GAS5, MEG3, FER1L4 and LINC00672) and oncogenic lncRNAs (CCAT2, BANCR, NEAT1, MALAT1, H19, Linc-RoR, TUG1, TDRG1 and PCGEM1) may be a few such examples." (PMID 30781521, 2019).
cancer (21 papers, 2015 to 2025). A tumor composed of atypical neoplastic, often pleomorphic cells that invade other tissues. "Due to the association of the FER1L4 pseudogene with the immune system, the abundance of immune cells, stromal cells, and cancer cells in patient samples was analyzed." (PMID 39764216, 2024). "Some cancer-specific lncRNAs, such as ABCC13, HOTAIR, LINC00472, and FER1L4 have also been reported to act as potential diagnostic and prognostic biomarkers in cancers." (PMID 29029488, 2017). "FER1L4 knockdown inhibited cancer cell proliferation and invasion capabilities but promoted apoptosis." (PMID 33868788, 2021). "FER1L4 knockdown increased the expressions of miR-106-5p and miR-372-5p that inhibited cancer progression." (PMID 33868788, 2021). "A recent study analyzed Fer1L4 in a pan-cancer study and demonstrated similar findings for a subset of RCC patients." (PMID 31965534, 2020). "Fer-1-like protein 4 (FER1L4) have recently attracted the researchers’ attention due to its involvement in the progression of cancer." (PMID 32140077, 2020). "The sponging of miRNAs by FER1L4 was studied in multiple cancers, including prostate and intestine, but it was never observed in CAFs." (PMID 33228208, 2020). "Studies on FER1L4 suggested that FER1L4 mainly exerted its function via sponging miRNAs in cancer cells." (PMID 32140077, 2020). "The results of the vast majority of the studies are consistent with a function of Fer1L4 as a tumor suppressor in multiple types of cancer." (PMID 32106631, 2020). "Lnc Fer1L4 was briefly investigated in ovarian cancer where it was described as downregulated in cancer cells in comparison to normal ovarian epithelial cells." (PMID 31443490, 2019). "Intriguingly, beyond a simple alteration, myoferlin, otoferlin and Fer1L4 expressions were negatively correlated with patient survival in some cancer types." (PMID 31443490, 2019). "However, intriguingly, plenty of literature documents context-dependent phenotypes of FER1L4 in human cancers." (PMID 34289835, 2021). "Previous study indicated that FER1L4 inhibited AKT activation in carcinoma by acting as miRNAs sponges to prevent miRNAs from binding their natural targets or promoting the expression of phosphatase and tensin homolog (PTEN), an antagonism of PI3K/AKT signaling pathway." (PMID 33604341, 2021). "Furthermore, Fer1L4 overexpression is an independent prognostic factor for overall, cancer-specific, and progression-free survival of patients with ccRCC." (PMID 31965534, 2020). "Previous studies have reported an anti-tumorigenic role of FER1L4 in several kinds of cancer." (PMID 31900200, 2020). "Initially, Fer1L4 long noncoding RNA was found to be selectively transcribed in human stomach tissue, however, later Fer1L4 was detected in multiple normal tissues surrounding malignant tumors." (PMID 32106631, 2020). "Notably, 86.1% lymph node metastatic tissues showed lower expression of FER1L4 compared with primary cancer tissues." (PMID 28418892, 2017). "FER1L4 is involved in various cancers including gastric cancer and colon cancer." (PMID 28418892, 2017). "In a human pan‐cancer analysis, it suggested FER1L4 may act as an oncogenic driver in cancers." (PMID 34289835, 2021). "A panel of five DNA methylation markers (FER1L4, ZNF671, ST8SIA1, TBX15, and ARHGEF4) detected 74% of EC cancer patients with an overall specificity of 91%." (PMID 35242243, 2022). "Thus, the Fer1L4 RNA may serve as a competing endogenous RNA and regulate the expression of PTEN via miRNA-mediated mechanisms inhibiting cancer cell proliferation and metastasis." (PMID 32106631, 2020). "An overview has demonstrated that all FERLIN genes are modulated in several cancer types, among which MYOFERLIN and FER1L4 genes are more frequently upregulated rather than being downregulated." (PMID 33868788, 2021).
FER1L4 also shares sentences with these, for which no sentence is quoted: lung carcinoma (4 papers); breast tumor (1); diabetes (1); Hepatitis (1); lymphoma (1); major depressive disorder (1); osteoarthritis (1); periodontitis (1); type 2 diabetes (1).